RN7SL470P (RNA, 7SL, cytoplasmic 470, pseudogene)
Gene: Miscellaneous RNA gene on chromosome 2 (70,075,014 to 70,075,272, reverse strand). Ensembl gene ENSG00000263669.
Homologues: Orthologues: chimpanzee Metazoa_SRP (83% identical), macaque Metazoa_SRP (83% identical). Paralogues in human: RN7SL510P (87% identical), RN7SL774P (87% identical), RN7SL811P (87% identical), RN7SL134P (86% identical), RN7SL96P (86% identical), Metazoa_SRP (85% identical), RN7SL190P (85% identical), RN7SL596P (85% identical), RN7SL163P (85% identical), RN7SL474P (85% identical), Metazoa_SRP (84% identical), RN7SL784P (84% identical), and 710 more.